NF2 (NF2, moesin-ezrin-radixin like (MERLIN) tumor suppressor)
Diseases named in the same sentence as NF2 in open-access papers (continued):
Sharing a sentence is not in itself a finding about the gene and the disease.
tumor (continued). "Merlin/NF2, a key activator of the Hippo pathway in growth control and regarded as a key tumor suppressor, is regulated by phosphorylation." (PMID 39688910, 2024). "Further studies should investigate possible risk factors for poor performance (e.g., tumour extension [inner ear plus IAC/CPA], NF2, “CI through tumour”, staged surgery, previous radiotherapy)." (PMID 38992191, 2024). "Sporadic and NF2-related VSs are frequently studied separately due to differences in tumor behavior, including their location (in the IAC and CPA), their appearance (lobular in NF2), and adherence to local structures." (PMID 38892775, 2024). "In the clinic, treatment with bevacizumab has been documented to lead to hearing improvement or tumor shrinkage in 30–60% of patients with NF2, and it is now approved for NF2 treatment in the UK." (PMID 38893082, 2024). "In cases of NF2, where tumor growth can lead to serious complications such as brainstem compression and cranial nerve dysfunction, stabilizing tumor growth becomes a crucial therapeutic objective." (PMID 39685944, 2024). "Electronic medical records were used to collect data on age at presentation, sex, location of tumour(s), extent of resection, histology, WHO grade, complications, outcomes and associated conditions, notably neurofibromatosis type 2 (NF2)." (PMID 39612013, 2024). "Together, our genomic analysis reveals the frequency, genomic positions, and types of NF2 mutations in SP-EPN in a large data set and identifies differences between NF2 mutations in SP-EPN and other tumor entities." (PMID 38265489, 2024). "For instance, fusions of oncogenic proteins TAZ, YAP1, and HIPK2 preserve their tumor-promoting function, while fusions of tumor suppressors, such as NF2, LATS1, FAT1, PTPN14, DCHS2, TAOK1, and TAOK3, results in loss of their function." (PMID 38499647, 2024). "One of the key pathways in which NF2 is thought to play a role as a tumor suppressor is the Hippo signaling pathway." (PMID 39796693, 2024). "While hearing and tumor volumetrics are paramount, symptoms related to NF2-related tumors and quality of life in relation to different management options are often overlooked." (PMID 38672561, 2024). "In this way, NF2 acts as a tumor suppressor through the Hippo signaling cascade by downregulating cell proliferation and survival, hallmark characteristics of all cancers." (PMID 39796693, 2024). "After 9 days of ALK-TKI therapy, sequencing analysis was performed, which identified several tumor suppressor genes, such as NF2 or MED12, and multiple candidate genes." (PMID 37917191, 2023). "As a tumor suppressor, NF2 interacts with and recruits the kinase LATS1 to the plasma membrane, which leads to the subsequent phosphorylation of LATS1 and the cytoplasmic retention of YAP25." (PMID 37080959, 2023). "In the past NF2 has been described as a tumor suppressor gene by inhibiting PI3K/AKT/mTOR signaling." (PMID 37917191, 2023). "Compared to sporadic VS, NF2-related VS arises at a younger age, almost always occurring bilaterally, and is often polyclonal, meaning that the tumor is comprised of several, distinct benign masses." (PMID 36975476, 2023). "Among the tumor suppressors, we found two (NF2, PTEN) were commonly shared between NEJF10 and HuH6 cells." (PMID 37414763, 2023). "The Hippo pathway is regulated by the merlin/neurofibromatosis type 2 (NF2), a well-studied tumor suppressor gene." (PMID 37190141, 2023). "The positive prognostic impact of S100 is mostly attributed to the confounding clinical factors gender, tumor location, NF2 status and WHO CNS grade." (PMID 35838837, 2023). "Deep mutational interaction perturbation scanning of NF2 with conformation-dependent interaction partners KDM1A, EMILIN, and PIK3R3 revealed two regions critical for NF2 tumor suppressor function." (PMID 37280085, 2023).
tumor (continued). "In this study, we have assessed the effect of >2,000 single amino acid substitutions in tumor suppressor NF2 on the interactions with four protein partners that bind NF2 in a conformation-dependent manner." (PMID 37280085, 2023). "Regarding tumor subtype, NF2 GA were found to be more common in uRCC and pRCC (P < 10e-10) as compared to other histologic types." (PMID 36917021, 2023). "Genes associated with a pro-inflammatory tumour microenvironment included TNF, IL6, IL18, NLRP3, IL1B and CASP1 which were also comparable between sporadic and NF2-SWN VS samples." (PMID 37680691, 2023). "For instance, in two studies, HEI-93 cells were xenografted into the mouse sciatic nerve (one of them with luciferase activity), and both showed less accurate anatomical features compared to NF2 characteristics but had fast tumor development." (PMID 37217995, 2023). "The importance of protein conformation for the tumor suppressor function of NF2 was recognized in early experiments." (PMID 37280085, 2023). "Here, macrophages were found to constitute one-third of the total cells within VS tumours from both NF2-SWN and sporadic patients." (PMID 37680691, 2023). "NF2 S518 phosphorylation by PAK1 or protein kinase A (PKA) leads to conformational changes of NF2 from active (closed) to inactive (open) forms, and inhibits NF2 tumor suppressor activity by blocking its head-to-tail interaction." (PMID 37118736, 2023). "A meta-analysis of eight studies using bevacizumab to treat NF2 reported tumor partial regression in 41% of patients, stable tumor size in 47%, and tumor progression in only 7%." (PMID 36549282, 2023). "VS is primarily caused by mutations in the neurofibromin 2 (NF2) gene disrupting production of merlin, a tumor suppressor." (PMID 37948527, 2023). "They showed that additional proliferative stimuli in the form of partial hepatectomy were required to induce emergence of overproliferating progenitor-like cells and tumor formation in mice with postnatal Nf2 deletion." (PMID 37174657, 2023). "Pearson correlation analysis shows that in this NF2 patient cohort, significant positive correlations between tumour volume and NAGM/NAWM Ktrans values were observed." (PMID 37765090, 2023). "The similarity of tumour immune microenvironments allows the potential for any new drugs shown to be effective in NF2-SWN VS to be rolled out to sporadic VS." (PMID 37680691, 2023). "NF2 (moesin–ezrin–radixin-like [MERLIN] tumor suppressor) is a member of the band 4.1 superfamily of proteins and is closely related to ezrin–radixin–moesin (ERM) proteins, which functions as links between the cell membrane and actin filaments." (PMID 37280085, 2023). "Among the expressed immune cell types, the xCell results showed a higher absolute value of myeloid cells in NF2 patients than in sporadic NF2-altered tumours (p = 0.008)." (PMID 37752594, 2023). "The total number of GA per tumor in the NF2mut cohort including NF2 GA and other co-occurring GA was 4.74, for a total of 911 GA." (PMID 36917021, 2023). "The NF2 gene expresses ten different isoforms resulting from alternative splicing, among which isoforms I and II are the major ones and both have tumor suppressive function." (PMID 37217995, 2023). "In contrast, the hypermetabolic and proliferative groups are also mainly NF2-altered and clinically malignant tumours." (PMID 37752594, 2023). "Elucidating NF2 conformation and its effect on interaction partners and protein function remains a pivotal research task to better understand NF2 tumor suppressor activities." (PMID 37280085, 2023). "In analogy to ERM proteins, NF2 function and tumor suppressor activity is thought to be controlled by conformation switches between an open or a closed state." (PMID 37280085, 2023). "To clarify immune infiltration and activity in NF2 patients’ tumours, we next quantified and deconvolved the immune infiltration using several methods, including xCell, ESTIMATE, and CIBERSORT." (PMID 37752594, 2023).
tumor (continued). "The gene list included Nf2, a well-known tumor suppressor, an outcome that validated the effectiveness of the screen in revealing genes altered by in vivo selection pressure." (PMID 37730636, 2023). "NF2/Merlin acts as an upstream regulator of the Hippo signaling tumor suppressor pathway that inhibits oncogenic YAP activity." (PMID 37174657, 2023). "In contrast, the overexpression of T567D Ezrin promoted these migratory behaviors, suggesting that Ezrin can inactivate NF2 tumor suppressor and promote metastasis." (PMID 37371090, 2023). "While bilateral ICS in patients with no genetic or clinical features of NF2 appear to be extremely rare, the possible explanations for this include mosaicism for NF2 or sporadic development of bilateral tumour development by chance alone." (PMID 37904024, 2023). "(ii) HMW-HA blocks cell migration by enhancing the co-association between NF2 (also known as Merlin protein) and CD44, which activates the tumor suppressor properties of CD44 (CD44-dependent mechanism)." (PMID 37511533, 2023). "This study highlights the power of systematic mutational interaction perturbation analysis to identify missense variants impacting NF2 conformation and provides insight into NF2 tumor suppressor function." (PMID 37280085, 2023). "How NF2 conformation is regulated and how NF2 conformation influences tumor suppressor activity is a largely open question." (PMID 37280085, 2023). "Tumour-associated macrophages indicated by Iba1 staining were found in cases of both diffuse tissue infiltration and vascular-associated niches at high levels in NF2-SWN and sporadic VS, identifying tumour microenvironment heterogeneity within each VS sample." (PMID 37680691, 2023). "Merlin deficiency due to NF2 mutations often results in the overactivation of the RAS/ERK pathway, therefore leading to tumor development." (PMID 38001599, 2023). "We next assayed the effects of the single amino acid substitutions on cell proliferation, a key feature of the tumor suppressor function of NF2." (PMID 37280085, 2023). "Using bulk transcriptomic analyses and cellular deconvolution, followed by confirmation with the first use of high-dimensional Hyperion IMC in VS, this study identified a robust similarity between the tumour immune microenvironments of NF2-SWN and sporadic VS." (PMID 37680691, 2023). "Neurofibromin-2 (NF2) promotes tumor suppression in the LATS1/2 canonical hippo pathway through MST1." (PMID 35804016, 2022). "For example, it has been shown that NF2 (neurofibromatosis 2 or Merlin) serves as a tumor suppressor by inhibiting KRAS and that NF2 mutations can cause persistent Ras signaling." (PMID 36077838, 2022). "NF2 patients remain a unique subgroup of VS patients with suspected lower rates of tumor control after radiation therapy." (PMID 35454823, 2022). "Compared to our own NF2 cohort of the same age group, the tumor size difference was even more pronounced (1.52 ± 2.49 cm3)." (PMID 35455534, 2022). "Neurofibromin 2 (NF2) is a tumor suppressor, but can result in frequent tumorigenesis when missense mutation occurs." (PMID 36550103, 2022). "LC was significantly lower in NF2 patients (p = 0.004) and in patients with higher tumor extension grade (p = 0.039)." (PMID 35454823, 2022). "Neurofibromatosis type 2 (NF2; MIM# 101000) is an autosomal dominant tumor predisposition condition, resulting from disruption of the NF2 gene." (PMID 35332608, 2022). "An example of the utility for this suggested evidence criteria can be seen for variant c.655G>A p.(Val219Met), which has been described in somatic samples and cases of mosaic NF2 identified through multiple tumor genotyping." (PMID 35332608, 2022). "NF2 promotes contact inhibition and tumor suppression by inhibiting mitotic signaling in the cell cortex." (PMID 35712491, 2022).
tumor (continued). "RICH1 protein inhibited the migration and sensitized the chemotherapeutic drugs, and RICH1 activated the kinase pathways of hippo signaling by displacing Amot-p80 protein from a tumor suppressor gene of NF2, named merlin." (PMID 36550571, 2022). "Experimental evidence suggest that the functional loss of NF2 in PM contributes to increased FAK expression and tumor cell invasion." (PMID 36362209, 2022). "When only considering these two mutated genes, the rate of conserved mutations between patient tumor and PDX tissue was very high, resulting in 100% for NF2 and 100% for VHL, respectively." (PMID 35800063, 2022). "Although an anti-vascular endothelial growth factor (VEGF) monoclonal antibody, bevacizumab, demonstrated partial tumor regression in 41% and improved hearing in 20% of NF2 patients, its chronic use is limited by renal toxicity." (PMID 35875610, 2022). "As in tumor growth, the positive effect of targeted anti-VEGF therapy on hearing development in patients with NF2-related VS indirectly suggests that VEGF is associated with hearing impairment." (PMID 36672540, 2022). "Recent clinical experiences have shown that treatment with bevacizumab resulted in tumor shrinkage and hearing improvement in a subset of patients with NF2." (PMID 36059985, 2022). "Alterations of BAP1 (70 %), CDKN2A (96 %), and NF2 (67 %) were detected at a higher frequency than reported for tumor biopsies." (PMID 36077838, 2022). "Mutation of the NF2 locus is also linked to TERT promoter mutations, which increase with tumor grade." (PMID 35892898, 2022). "We assessed tumour recurrence in correlation with extent of resection (EOR), histopathological findings, tumour location, and NF2 alteration." (PMID 35570314, 2022). "They play a direct role in tumorigenesis by promoting tumor vascularization and enhancing PD-L1 and NF2 expression." (PMID 35892898, 2022). "This, therefore, reinforces the likelihood that NF2 enacts its tumour suppressive role via the ability to act as a sensor of cellular stress and regulate a response to both serum/glucose starvation and contact inhibition." (PMID 35119068, 2022). "A clinical trial using a VEGFR-1/2 peptide vaccine was also conducted in patients with progressive NF2-derived Schs, showing hearing improvement and tumor volume reduction." (PMID 35628268, 2022). "The tumor suppressor NF2/Merlin, localized in the cell membrane, tight junctions, and cytoskeleton, also mediates intercellular signaling." (PMID 36497453, 2022). "Such intercellular interaction activates the Hippo pathway through NF2/Merlin tumor suppressor, thus inhibiting the transcriptional activity of YAP, and there are many genes regulating ferroptosis which is the target genes of YAP." (PMID 36387147, 2022). "NF2 is ranked by NDSI as the strongest mixed tumour suppressor and 3rd strongest CNA-based tumour suppressor." (PMID 35975235, 2022). "Multiple tumor driver genes that are associated with spermatogenesis pathway such as mTOR, EZH2, NF2, DCC and MLF1 had high enrichment score in the EGFR group." (PMID 35428753, 2022). "The study found that silencing of NF2 activates ferroptosis-related pathways in GPX4-knockout tumor mice." (PMID 35911967, 2022). "Other targeted therapies have been slow to emerge for MPM, which lacks common oncogenic drivers, and instead is characterised by loss-of-function mutations in tumour suppressors, most commonly BAP1, P16 and NF2." (PMID 36497318, 2022). "A study in 2010 demonstrated that the Mer/NF2 tumour suppressor and the YAP oncoprotein function antagonistically to regulate liver development." (PMID 36362947, 2022). "The earliest study looking at the effect of tumor growth over time does show decreased WRSs and increased PTAs in both NF2 and sporadic VS patients." (PMID 35372070, 2022). "NF2 gene generates merlin, also known as schwannomin, a cytoskeletal protein that functions as a tumor suppressor." (PMID 35291225, 2022).
tumor (continued). "The mutations of NF2 and VHL are present in both the PDX model and the corresponding primary tumor in the Tübingen cohort (crossed squares)." (PMID 35800063, 2022). "We conclude that NF experts and patient representatives consent to prioritise development of drug trials for MPNST, benign peripheral nerve sheath tumours, cutaneous manifestations and HGG for NF1; tumours for NF2; and pain for SWN." (PMID 33903738, 2021). "As the upstream gene of the Hippo pathway, NF2 is considered to be a tumour suppressor in multiple human tumours." (PMID 33219752, 2021). "Besides, Neurofibromin 2 (NF2/Merlin/schwannomin) is a classical tumor suppressor and naturally occurring mutations in the FERM domain could transform it into a profound suppressor, which can inhibit the cGAS-STING pathway by blocking STING-mediated DNA sensing." (PMID 35046953, 2021). "Patient 5 with NF2 and bilateral deafness was observed until the ipsilateral residual tumor after partial tumor resection had remained stable for some years." (PMID 33044580, 2021). "As a tumor suppressor gene, NF2 can be activated by E-cadherin and inhibits ferroptosis in endothelial cells." (PMID 34868391, 2021). "Thereafter, we comprehensively evaluated the associations between tumor location (embryological origin), pathological diagnosis (histological type), and driver mutations including AKT1, KLF4, SMO, POLR2A, and NF2 mutations." (PMID 33772057, 2021). "Our analysis revealed tumor-infiltrating CD8+ T-cells, particularly CD8+ effector memory T-cells, were mainly enriched in MPM harboring LATS1/2 mutation, compared with NF2-mutant MPM and other cancer types." (PMID 33805359, 2021). "Of note, the variant frequencies in the clonal tumor population (ARID2, SETD2, and TERT promoter) and in the subclonal population (NF2) were validated by targeted NGS for this patient." (PMID 34261524, 2021). "We observed this cooperative effect across multiple different models and phenotypes: loss of NF2 synergized with RIT1M90I in the PC9 erlotinib resistance assay and promoted tumor formation of human SALE cells in vivo." (PMID 34373451, 2021). "Strikingly, we found a subclonal tumor population present in both biopsies in patient T333HP supported by six variants, including NF2." (PMID 34261524, 2021). "As discussed in the prior sections, as the molecular pathology is being unraveled, we will be able to design better drugs for the tumor types in NF2 patients." (PMID 33445724, 2021). "In contrast, when transplanted subcutaneously in mice, three HOMCs with NF2 knockdown formed a tumor mass, confirming that NF2 is an important tumor suppressor gene in MM cells." (PMID 34663305, 2021). "In MM, tumor development is nevertheless characterized by a low mutation rate despite major structural chromosomal rearrangements driving oncogenesis (BAP1, NF2, CDKN2AB)." (PMID 34199066, 2021). "Collectively, these analyses suggested that different tumor-infiltrating immune cell patterns exist between dysregulation of NF2 and Hippo-YAP signaling in MPM." (PMID 33805359, 2021). "NF2 inactivation gives to the tumor a genomic instability and a peculiar multiple localization in the hemispheres." (PMID 34679551, 2021). "The NF2 protein, or better known as the Merlin protein (moesin-ezrin-radixin-like protein), functions as a tumour suppressor through impacting mechanisms related to proliferation, apoptosis, survival, motility, adhesion, and invasion." (PMID 33737684, 2021).